CDC42 (cell division cycle 42)
Diseases named in the same sentence as CDC42 in open-access papers (continued):
Sharing a sentence is not in itself a finding about the gene and the disease.
lymphopenia (2 papers, 2020 to 2023). Reduction in the number of lymphocytes. "A CDC42 mutation in a Takenouchi-Kosaki syndrome patient was accidentally found in an infant with failure to thrive, lymphopenia and lymphedema by whole exome sequencing for PID suspicion." (PMID 32265901, 2020). "We report a novel CDC42 missense variant (c.46A > G, p.Lys16Glu) resulting in infection and HPV-driven carcinogenesis in the mosaic mother and impaired thymopoiesis and profound T cell lymphopenia in the heterozygous daughter identified through newborn screening for SCID." (PMID 37581646, 2023).
malaria (2 papers, 2022 to 2025). Malaria is a serious and sometimes fatal disease caused by a parasite that commonly infects a certain type of mosquito which feeds on humans. "Compared with those in the control group, the expression levels of key node proteins of Fcγ R-mediated phagocytosis, including SYK, PI3K, PLCγ2, p-MARCKS, CDC42, and RAC, in the spleen samples of the malaria group decreased significantly (P< 0.01 or< 0.05)." (PMID 41425569, 2025). "Two compounds inhibiting the closely related Rho GTPase CDC42 were not active against malaria parasites, thus excluding possible off-target effects on this GTPase." (PMID 34723630, 2022). "Compared with those in the malaria group, the expression levels of proteins SYK, PI3K, PLCγ2, and RAC in the spleens of mice in the ZF-CQ group increased significantly (P< 0.01 or< 0.05), and the expression levels of proteins p-MARCKS and CDC42 showed an upward trend." (PMID 41425569, 2025). "These compounds were not active against malaria parasites, at neither sexual nor asexual stages, excluding that the antimalarial activity of the Rac1 inhibitors is due to off-target effects on CDC42." (PMID 34723630, 2022).
metastatic tumors (2 papers, 2014 to 2023). "Research on BC specimens demonstrated reduced TTC17 and increased CDC42 in metastatic tumors and lymph nodes, and low TTC17 expression was linked to more aggressive clinicopathologic characteristics." (PMID 36895029, 2023).
Myocardial fibrosis (2 papers, 2021 to 2022). "Inhibition of CDC42 expression effectively alleviates myocardial fibrosis and hypertrophy in patients with salt-sensitive hypertension." (PMID 35537778, 2022). "The inhibition of CDC42 decreases myocardial fibrosis and hypertrophy in salt-sensitive hypertension." (PMID 33824277, 2021).
myotonic dystrophy (2 papers, 2021 to 2023). An inherited progressive disorder affecting the muscles. "Acting downstream of the Cdc42 GTPase, the myotonic dystrophy-related Cdc42-binding kinases MRCKα, MRCKβ, and MRCKγ have recently emerged as important players in cytoskeleton regulation through the phosphorylation of proteins such as the regulatory myosin light chain proteins." (PMID 36831201, 2023). "An intermediate candidate for the activation of RLC by Cdc42 may be the myotonic dystrophy-related Cdc42-binding kinase (MRCK; Unbekandt and Olson, 2014; Zhao and Manser, 2015); however, further studies are needed to establish this hypothesis." (PMID 34512376, 2021).
Noonan syndrome (2 papers, 2021 to 2022). Noonan Syndrome (NS) is characterized by short stature, typical facial dysmorphism and congenital heart defects. "Recently, nine different CDC42 missense mutations causing a phenotype resembling Noonan syndrome have been identified by researchers." (PMID 34830479, 2021).
sarcoma (2 papers, 2021 to 2024). A usually aggressive malignant neoplasm of the soft tissue or bone. "miR-130b enhanced the malignant phenotype of ewing sarcoma cells by activating the CDC42/PAK1 signaling pathway." (PMID 34289832, 2021).
tuberculosis (2 papers, 2022 to 2024). A chronic, recurrent infection caused by the bacterium Mycobacterium tuberculosis. "The bacillus Calmette–Guerin (BCG) vaccine for tuberculosis (TB) has been shown to be effective in the treatment of bladder cancer by macropinocytic delivery, which is dependent on RAC1, CDC42, and its effector PAK1." (PMID 39000072, 2024).
type 1 diabetes (2 papers, 2017 to 2021). "Small-molecule inhibitors of RhoB have not been described, although molecules that target RhoA, Rac and Cdc42 have been, including Rac inhibitors studied in models of type 1 diabetes and collagen-induced arthritis." (PMID 28882929, 2017).
adenoma (1 paper, 2005). A neoplasm arising from the epithelium. "The average expression levels of two genes (Cdc42 and Galectin-1) and four genes (p21, Erk1, Mucin 3, and Laminin β-3) were significantly lower and higher, respectively, in the flat-type adenoma group than those in the early invasive carcinoma group." (PMID 15785755, 2005).
aging (1 paper, 2024). A developmental process that is a deterioration and loss of function over time. "Skin aging has been associated with the onset of various skin issues, and recent studies have identified an increase in Cdc42 activity in naturally aging mice." (PMID 39289787, 2024).
AIDS (1 paper, 2013). A syndrome resulting from the acquired deficiency of cellular immunity caused by the human immunodeficiency virus (HIV). "In the human fungal pathogen Penicillium marneffei, which causes disseminated disease in AIDS patients, RasA has been shown to act through cflA (Cdc42) to control yeast cell polarization and conidial germination." (PMID 23950731, 2013).
alopecia (1 paper, 2019). Hair loss usually from the scalp. "In addition, postnatal HF defects leading to alopecia have been reported for both RAC1 and CDC42, and for CDC42, defects in basement membrane assembly, hair differentiation and WNT signaling have also been described." (PMID 31556874, 2019).
autism (1 paper, 2021). Persistent deficits in social interaction and communication and interaction as well as a markedly restricted repertoire of activity and interest as well as repetitive patterns of behavior. "A role for GTPases in neurodevelopmental disorders, especially autism is attested by the association of RhoA and CDC42 genes to ASD." (PMID 33925474, 2021).
Autoimmunity (1 paper, 2011). The occurrence of an immune reaction against the organism's own cells or tissues. "Our findings suggest that while Cdc42 is required for thymopoiesis, it plays a restrictive role in effector and memory T cell differentiation and autoimmunity." (PMID 21455314, 2011). "It would be interesting to assess how regulatory T cells act on memory phenotype T cells to suppress the development of spontaneous autoimmunity in Cdc42−/− mice." (PMID 21455314, 2011). "Collectively, these data establish that Cdc42 is critically involved in thymopoiesis and plays a restrictive role in effector and memory T cell differentiation and autoimmunity." (PMID 21455314, 2011). "While essential for TCR clustering and actin polarization in the course of mature IS formation, Cdc42 suppresses CD4+ Th1 (but not Th2) and CD8+ effector and memory T cell differentiation and autoimmunity." (PMID 21455314, 2011).
autoinflammatory syndrome (1 paper, 2023). A group of disorders of the innate immune system characterized by attacks of seemingly unprovoked inflammation without significant levels of either autoantibodies or autoreactive T cells more characteristic of autoimmune disease. "Differently than the NOCARH and HLH responsive to anti-IFNγ caused by the p.R186C mutation in the CDC42 gene, novel additional mutations in CDC42 C-terminus region have been recently associated to a clinical autoinflammatory syndrome responsive to IL-1 inhibitors." (PMID 37187762, 2023).
autosomal dominant retinitis pigmentosa (1 paper, 2011). Autosomal dominant retinitis pigmentosa (RP) is an autosomally dominant inherited retinal dystrophy leading to progressive loss of the photoreceptors and retinal pigment epithelium and resulting in blindness usually after several decades. "Photoreceptor degeneration was studied in a mouse model for autosomal dominant retinitis pigmentosa (VPP) with or without a rod-specific knockdown of Cdc42, as well as in wild-type and Cdc42 knockdown mice after light exposure." (PMID 22128240, 2011).
B-cell lymphoma (1 paper, 2020). "Rac and Cdc42 are often dysregulated in cancer due to hyperactivation by guanine nucleotide exchange factors (GEFs), belonging to both the diffuse B-cell lymphoma (Dbl) and dedicator of cytokinesis (DOCK) families." (PMID 32322580, 2020).
bacteremia (1 paper, 2021). "In 2021, CDC42 deficiency was shown to be associated with recurrent pneumonia, otitis media, and bacteremia." (PMID 34912812, 2021).
Burkitt lymphoma (1 paper, 2019). A rare form of malignant mature B-cell non-Hodgkin lymphoma. "Evidence showed that Cdc42 promoted survival of Burkitt lymphoma cells through regulating major histocompatibility complex (MHC) and myosin light chain (MLC)." (PMID 30621321, 2019). "Recently, involvement of Cdc42 in Burkitt lymphoma cells resistance to ascorbate-induced cytotoxicity was discovered." (PMID 30621321, 2019).
carcinosarcoma (1 paper, 2016). A malignant tumor composed of a mixture of carcinomatous and sarcomatous elements. "Therefore, we tested the relative requirements for Rac, Cdc42 and Rho and their effectors on electrotactic guidance of blebbing and lamellipodia forming sublines of WC 256 carcinosarcoma cells." (PMID 26863616, 2016).
cerebral cavernous malformation (1 paper, 2021). A disorder characterized by malformations in the structure of the capillaries in the brain. "Genetic mouse models of cerebral cavernous malformations (CCM) further support the assumption of an inverse correlation between ERK5 and CDC42 activity." (PMID 34299213, 2021).
Charcot-Marie-Tooth disease (1 paper, 2017). An inherited degenerative disorder involving the peripheral nerves. "Though primarily known for its role in myelination and Charcot-Marie Tooth Disease, shRNAs against the CDC42 GEF, Frabin, also decreased spine length." (PMID 28114311, 2017).
Cirrhosis (1 paper, 2019). A chronic disorder of the liver in which liver tissue becomes scarred and is partially replaced by regenerative nodules and fibrotic tissue resulting in loss of liver function. "Cytotines from cirrhosis induces the PTEN/AX2/Cdc42 signalling pathway, which promoted actin cytoskeleton disassembly in the lung." (PMID 31144461, 2019).
cognitive decline (1 paper, 2021). "However, there is no information correlating CDC42 expression in the blood to cognitive decline." (PMID 34199148, 2021).
coloboma (1 paper, 2024). An abnormality in which a part of a structure in one or both eyes is missing. "Here we identify a novel essential function for Cdc42 during eye morphogenesis in mouse; in Cdc42 mutant eyes expansion of the ventral optic cup is arrested, resulting in microphthalmia and a wide coloboma." (PMID 39650797, 2024).
colorectal polyp (1 paper, 2023). "The present study's findings suggest that the expression pattern of CDC42, TAGLN, and GSN genes was significantly increased during the transformation of normal tissue to polyp lesions, indicating their potential as prognostic biomarkers for colorectal polyp development." (PMID 37365287, 2023).
cone retinal dystrophies (1 paper, 2023). "Our observations identify GRF2 and CDC42 (but not RAC1) as key regulators of retinal processes controlling cone photoreceptor nuclear positioning and survival, and support the notion of GRF2 loss-of-function mutations as potential drivers of cone retinal dystrophies." (PMID 37947653, 2023).
Crohn disease (1 paper, 2022). A gastrointestinal disorder characterized by chronic inflammation involving all layers of the intestinal wall, noncaseating granulomas affecting the intestinal wall and regional lymph nodes, and transmural fibrosis. "For instance, CDCD42 was negatively correlated with disease activity reflected by pediatric Crohn’s disease activity index in pediatric IBD patients, although no relevant studies have reported the correlation of CDC42 with disease activity or inflammation in RA patients." (PMID 34859333, 2022).
deafness (1 paper, 2016). An inherited or acquired condition characterized by the complete loss of the ability to hear from one or both ears. "We previously reported inner ear HC‐specific Cdc42‐knockout (KO) mice, which show progressive deafness in parallel with HC loss with stereocilia degradation, including short, elongated, fused stereocilia." (PMID 27707755, 2016).
dermatophytosis (1 paper, 2024). A common fungal infection of the stratum corneum of the skin, hair, or nails by a dermatophyte. "Through chemical screening and establishment of a novel genetic technique to repress gene expression in Trichophyton rubrum, the primary causal fungus of dermatophytosis, we demonstrated that fungal Cdc42 and Rac GTPases are promising antifungal drug targets." (PMID 38952678, 2024). "Thus, the use of TrCdc42 and TrRac inhibitors for the treatment of dermatophytosis could potentially cause adverse effects, such as immunosuppression, infections, and acute cardiovascular toxicity, through the inhibition of human Cdc42, Rac, and/or off-targets." (PMID 38952678, 2024).
dysplasia (1 paper, 2021). A usually neoplastic transformation of the cell, associated with altered architectural tissue patterns. "EXC-5 is an orthologue of the faciogenital dysplasia-associated (FGD) family of RhoGEFs that can activate Cdc42 in biochemical and cell culture assays, and EXC-5 has been proposed as an activator of CDC-42 in the excretory cell." (PMID 33687331, 2021).
eczema (1 paper, 2025). "Moreover, allergic presentations, particularly eczema (72.7%) were significantly more prevalent in the defective CDC42 pathway rather than RAC2 pathway." (PMID 40860338, 2025).
experimental autoimmune encephalomyelitis (1 paper, 2020). An autoimmune demyelinating disease of the central nervous system that is produced experimentally in animals by the injection of homogenized brain or spinal cord in Freund's adjuvant. "A recent study indicates that LRCH1 act to restrain PKCα-DOCK8-Cdc42 module-mediated T cell migration in experimental autoimmune encephalomyelitis, through competing with Cdc42 for interaction with DOCK8." (PMID 32631435, 2020). "It was recently reported that LRCH1 competes with Cdc42 for interaction with DOCK8 and restrains T cell migration in experimental autoimmune encephalomyelitis." (PMID 32631435, 2020).
familial Mediterranean fever (1 paper, 2021). Familial Mediterranean fever (FMF) is an autoinflammatory disorder characterized by recurrent short episodes of fever and serositis resulting in pain in the abdomen, chest, joints and muscles. "On the other hand, defective dynamics of actin polymerization leads to abnormal activation of pyrin inflammasome and autoinflammation, as in PAPA syndrome, Familial Mediterranean Fever, Hyper-IgD syndrome, and CDC42 deficiency." (PMID 33809703, 2021).
female infertility (1 paper, 2018). Diminished or absent ability of a female to achieve conception. "With regards to female germ cell development, a previous study reported that deletion of CDC42 in activated oocytes via follicle-specific Zp3-Cre disrupts oocyte maturation and leads to complete female infertility." (PMID 29976179, 2018).
fronto-temporal dementia (1 paper, 2018). "We showed here that Rac1 increased in AD patients with MMSE< 18 and, in a recent work, that Cdc42 decreased in fronto-temporal dementia patients." (PMID 30005699, 2018).
gallbladder cancer (1 paper, 2023). "Moreover, considering that PAK4 shows its kinase activity upon interaction with CDC42 and CDC42 signaling is regulated by PHF8, there might be potential relationships between the roles of PAK4 and PHF8 in the progression of gallbladder cancers." (PMID 36980457, 2023).
gestational trophoblastic disease (1 paper, 2017). "Even when PAK2 had being poorly studied in PE, we know that it is directly involved in gestational trophoblastic disease and that endothelial cells PAK and/or CDC42 are directly involved with KDR and consequently essential for endothelial cells organization." (PMID 28789679, 2017).
Glucose intolerance (1 paper, 2021). Glucose intolerance (GI) can be defined as dysglycemia that comprises both prediabetes and diabetes. "In further support of a key role for Cdc42 in the β-cell in regard to whole body glucose homeostasis, mice lacking the Cdc42 gene in pancreatic β-cells (Rip-CDC42cKO) were shown to display glucose intolerance and decreased GSIS, without alterations to islet morphology." (PMID 34203728, 2021).
HCMV infection (1 paper, 2025). "When infected HTMC cells were assessed for Rho family low molecular weight G protein by activation assays, our results showed that HCMV infection activated Cdc42 and Rac1." (PMID 40353220, 2025). "Our study highlighted the distinct profiles of the Rho family GTPases-Cdc42, Rho-A, and Rac1 following HCMV infection, especially in the context of IL-8/CXCR2 signaling." (PMID 40353220, 2025). "Together with the network analyses and cell contraction assays, IL-8/CXCR2 using Cdc42 appeared to play crucial roles in HTMCs dynamics after HCMV infection." (PMID 40353220, 2025). "We have analyzed the activation profiles of Cdc42, Rho-A, and Rac1 after HCMV infection." (PMID 40353220, 2025). "Our findings emphasize the unique contributions of the coordinate activation of Cdc42 and Rac1, especially in CXCR2 and CCR2-mediated activation after HCMV infection." (PMID 40353220, 2025). "HCMV infection also induced cell contraction that was dependent on CXCR2, but not on CCR2, and it involved the activation of Rac1/Cdc42." (PMID 40353220, 2025).
Hernia (1 paper, 2020). "Together, our results show that PIK3R1, PTPN11, TGFBR1, CDC42, and SOS1 are probably the most essential proteins involved in human hernia formation." (PMID 31910207, 2020).
Hodgkins lymphoma (1 paper, 2020). A heterogeneous group of malignant lymphoid neoplasms of B-cell origin characterized histologically by the presence of Hodgkin and Reed-Sternberg (HRS) cells in the vast majority of cases. "It is important to emphasize that Hodgkin's lymphoma is described for the first time in the medical literature in a pediatric patient with the novel p.Cys81Tyr mutation in the CDC42 gene." (PMID 32231661, 2020).
Hyperinsulinemia (1 paper, 2023). An increased concentration of insulin in the blood. "Even though the precise relationship between Cdc42, insulin, and leptin in blood vessels is unknown, it is reasonable to assume that Cdc42 activation is linked to vascular remodeling caused by age-related hyperinsulinemia and hyperleptinemia." (PMID 38068822, 2023).
Inguinal hernia (1 paper, 2020). Protrusion of the contents of the abdominal cavity through the inguinal canal. "We discovered that PIK3R1, PTPN11, TGFBR1, CDC42, SOS1, and KRAS were the most essential inguinal hernia-causative proteins and UBC, GRB2, CTNNB1, HSP90AA1, CBL, PLCG1, and CRK were listed as the most commonly-involved downstream proteins." (PMID 31910207, 2020). "Five essential proteins (PIK3R1, PTPN11, TGFBR1, CDC42, and SOS1) and three downstream common proteins (UBC, GRB2, and CTNNB1) were found to be related to inguinal hernia development." (PMID 31910207, 2020). "Additionally, others also show that inguinal hernia-related essential proteins, PTPN11, CDC42, and SOS1 regulate the RAS/MAPK signaling pathway, which is another downstream effector of RTKs." (PMID 31910207, 2020). "Thus, proteins PIK3R1, CDC42, TGFBR1, PTPN11, UBC, CTFR, and SOS1 may play an important role in the inguinal hernia PPI network." (PMID 31910207, 2020).
insulinoma (1 paper, 2019). "Cell division control protein 42 (Cdc42) and the microRNA (miRNA) miR-29 have important roles in β-cell proliferation and glucose-stimulated insulin secretion (GSIS), which we further explored using the mouse insulinoma cell line MIN6." (PMID 31662747, 2019).